KRT7 (keratin 7)
Diseases named in the same sentence as KRT7 in open-access papers (continued):
Sharing a sentence is not in itself a finding about the gene and the disease.
pancreatic cancer (43 papers, 2007 to 2025). "A study has demonstrated that the upregulation of KRT7 in pancreatic cancer is associated with the expression of immune checkpoints, including CD274, CD276, HAVCR2 (hepatitis A virus cellular receptor 2), and VTCN1." (PMID 38260844, 2023). "Our prognostic model containing four DEGs (DSG3, ARNTL2, NUSAP1 and KRT7) was used to determine the risk scores of pancreatic cancer patients, and patients with high risk scores were found to exhibit poor overall survival." (PMID 32081836, 2020). "KRT7, the most important risk gene in this model, was significantly associated with poor prognosis of pancreatic cancer in the TCGA dataset, and their cohort indicated that high KRT7 expression may be responsible for immunosuppression in the pancreatic TME." (PMID 37790755, 2023). "Zhang reported that the genes MET, MUC16, and KRT7 in the model had high expression levels in pancreatic tumor tissues as validated by RT-qPCR." (PMID 39127853, 2024). "RT-qPCR validated that MET, MUC16, and KRT7 in the model had higher expression levels in pancreatic tumour tissues." (PMID 37815881, 2023). "In this study, we used TCGA and GEO datasets to construct 5-mRNA signature (ANKRD22, ARNTL2, DSG3, KRT7, PRSS3) that is associated with the prognosis of pancreatic cancer patients." (PMID 36906533, 2023). "In other cancer cells, up-regulation of KRT7 expression has been observed in various types of cancer, including breast, ovarian, lung, and pancreatic cancers." (PMID 37954148, 2023). "Previous studies have indicated that KRT7 is overexpressed in many cancers, including ovarian, gastric, colorectal, and pancreatic cancer, which can facilitate the migration and invasion of cancer cells." (PMID 35974300, 2022). "Using these approaches, we found that overall survival was the main clinical trait associated with the transcriptome profiles of pancreatic cancer patients, and that DSG3, ARNTL2, NUSAP1 and KRT7 were independent prognostic factors." (PMID 32081836, 2020). "The coexpression of pancreatic cancer-enriched cytokeratins (Krt7 and Krt19) in single cells expressing these ECM gene products excludes the possibility that these represent circulating tumor-derived fibroblasts." (PMID 25242334, 2014). "Furthermore, single-cell analysis revealed that MET, MUC16, and KRT7 were mainly expressed in the microenvironment of pancreatic cancer cells." (PMID 39127853, 2024). "The subcutaneous nodules biopsied showed carcinomatous involvement with cytokeratin 7 (CK7 typically expressed in epithelial cancers such as breast, lung, ovarian, and pancreatic cancers), but the immunohistochemical staining was inconclusive regarding the primary origin of the neoplasm." (PMID 39195333, 2024). "The current study found KRT7 was remarkably overexpressed in pancreatic tumours and related to a worse prognosis, suggesting KRT7 might function as a possible therapeutic target for PC." (PMID 37815881, 2023). "High expression of EPYC, ANKRD22, ARNTL2, DSG3, KRT7, PRSS3 and MET predict poor prognosis of pancreatic cancer patients." (PMID 38184732, 2024). "Based on GEPIA database, we found that mRNA expression of MET, KRT7, and MUC16 was remarkably higher in pancreatic tumour than in normal tissues." (PMID 37815881, 2023). "Compared to pancreatic normal tissues, the expression levels of MET, KRT7, and MUC16 were remarkably higher in pancreatic tumour tissues." (PMID 37815881, 2023). "For instance, in pancreatic tumors, the expression of SOX9 positively correlates with the expression of epithelial phenotype genes (CDH1, KRT7, KRT18, and KRT19) and negatively correlates with the expression of the mesenchymal phenotype gene VIM." (PMID 35884771, 2022). "To further validate our human pancreas cancer CAM model, we compared the expression of the cytokeratin-7, -19, -20, CD56, CEA and Ki67 using immunohistochemistry to human PDAC." (PMID 24040391, 2013).
pancreatic cancer (continued). "Interestingly, our results reveal that, in contrast to KRT7, the expression of YWHAZ and GPRC5A genes demonstrates a relatively stronger correlation with B cell infiltration in pancreatic cancer." (PMID 38634049, 2024). "A machine learning based-study reported that the 5-gene signature including ANKRD22, ARNTL2, DSG3, KRT7, PRSS3 performed well on both our chosen training dataset and validation dataset and provided a new way to predict the prognosis of pancreatic cancer patients." (PMID 38184732, 2024). "carried out a comprehensive investigation on pancreatic cancer and found that WT1, a transcription factor, interacts with the KRT7 gene, leading to its expression by binding to a specific site in the 562-570 bp region upstream of the KRT7 promoter." (PMID 38260844, 2023). "As expected, epithelial markers (Krt7, Krt8, Krt18, Krt19, Epcam, Egfr, Cdh1) were highly expressed in primary pancreatic tumors and in the cancer cell line NB508 and nearly absent in the nonepithelial MEFs and in normal WBCs." (PMID 25242334, 2014). "The final pathology report on the left corpus luteum cyst located a small focus of moderately differentiated adenocarcinoma in corpus luteum staining strongly positive for Cytokeratin 7 (CK7) and negative for Cytokeratin 20 (CK 20) suggesting a primary gastric or pancreatic carcinoma." (PMID 24708577, 2014). "Cytokeratin 7 was not expressed in any of the CTCs examined from 10 pancreatic cancer patients." (PMID 22187035, 2012). "Based on the existing literature and our experimental results, we hypothesized that KRT7 and KRT19 are involved in EMT as epithelial components, while CXCL5 and IGF2BP3 act as regulatory factors to regulate EMT, thereby promoting the invasion and metastasis of pancreatic cancer." (PMID 37371833, 2023).
hepatocellular carcinoma (39 papers, 2002 to 2026). A malignant tumor that arises from hepatocytes. "The tumor entity was confirmed by H&E and by immunohistochemical staining for HepPar1, as a marker for hepatocellular carcinoma, cytokeratin 7 (CK7), used as a marker for cholangiocarcinoma, and Picro-Sirius Red, as collagen stain." (PMID 39820815, 2025). "For example, squamous cell carcinomas of the lung or hepatocellular carcinomas may have a certain amount of cytokeratin 7, which is otherwise typically detected in ACs." (PMID 40634392, 2025). "Further evidence of cholangiocarcinoma and/or hepatocellular carcinoma in this PCK model was evidenced by rich cytokeratin 7 staining restricted to intrahepatic ducts in the PCK rat and corroborated by Ca19-9 staining of both intrahepatic ducts and hepatic parenchyma in the PCK but not WT cohort." (PMID 30939854, 2019). "Some primary HFH, but not Huh-7.5 hepatoma cells, appeared to differentiate towards a cholangiocyte lineage within the gels, based on histological appearance and cytokeratin 7 (CK7) mRNA and protein expression." (PMID 20376322, 2010). "In immunohistochemical (IHC) tests, the adenocarcinoma cells were positive for cytokeratin-7 (CK7), cytokeratin-19 (CK19), CD56, and epithelial membrane antigen (EMA), but negative for hepatocellular carcinoma markers such as Glypican-3 (date not shown)." (PMID 30478801, 2018).
cholangiocarcinoma (38 papers, 2002 to 2026). A carcinoma that arises from the intrahepatic biliary tree (intrahepatic cholangiocarcinoma) or from the junction, or adjacent to the junction, of the right and left hepatic ducts (hilar cholangiocarcinoma). "The findings indicated that the levels of the genes reported as phenotypic markers for cholangiocarcinoma, including Epcam, Kit, Krt7, Krt19, and Muc1, were upregulated, suggesting that the cancerous lesions in the liver appeared to be cholangiocarcinoma." (PMID 37834032, 2023). "Consequently, these images demonstrated that at the invasive margin in replacing HGP, Keratin 7-positive cholangiocarcinoma cells were closely opposed to CD34-positive sinusoid-like vessels (vessel co-option) in addition to TAGLN-positive tumoral vessels." (PMID 38960952, 2024). "This supports the non-neoplastic, regenerative nature of RHP.CK7 (Cytokeratin 7) positive staining in bile ducts confirms the preservation of biliary structures, ruling out cholangiocarcinoma." (PMID 40519910, 2025). "These metastases were positive for PAX8, that is a well-established marker for primary and metastatic RCC and CDH16, which is a specific renal protein, while they were negative for the bile ducts and cholangiocarcinoma marker CK7 (Cytokeratin 7), consistent with their renal origin." (PMID 27668431, 2016).
renal cell carcinoma (38 papers, 2007 to 2025). "On the other hand, high KRT7 expression was associated with a better prognosis in renal cell carcinoma, as an example." (PMID 35406395, 2022). "The neoplastic cells were focally weakly immunoreactive (1+, cytoplasmic staining) cytokeratin 7, renal cell carcinoma antigen, and colloidal iron." (PMID 19450277, 2009). "Cytokeratin 7 (CK7) staining is typically very minimal in oncocytomas, whereas renal cell carcinoma can be diffusely positive in a membranous distribution." (PMID 39417067, 2024). "Among the commonly used immunohistochemical markers, CA9 and cytokeratin 7 are the most helpful immunostainings for differentiating TFE3-rearranged renal cell carcinoma from common renal cell tumors as they are frequently negative in TFE3-rearranged renal cell carcinoma." (PMID 39410016, 2024). "Moderately differentiated metastatic clear cell renal cell carcinoma was immunohistochemically confirmed - tumor immunophenotype showed positivity for RCC and CD10, and negative for cytokeratin 7 (CK7), cytokeratin 20 (CK20), vimentin and TG." (PMID 41584596, 2025).
urothelial carcinoma (37 papers, 2006 to 2026). A malignant neoplasm derived from the transitional epithelium of the urinary tract (urinary bladder, ureter, urethra, or renal pelvis). "Pathology revealed urothelial carcinoma with T2 disease at the lower ureter, plus spreading cytokeratin 7+ and cytokeratin 20+ pagetoid cells clustered within the epidermis indicative of secondary Paget's disease." (PMID 40336751, 2025). "The malignant cells were positive for p63 and negative for PSA, cytokeratin 7 (CK7), and cytokeratin 20 (CK20); therefore, a diagnosis of poorly differentiated urothelial carcinoma was favored." (PMID 27648316, 2016). "Supraclavicular node biopsy supported the diagnosis of stage IV urothelial carcinoma with GATA3 positive, cytokeratin 7 (CK 7) positive, and cytokeratin 20 (CK 20) negative immunohistochemistry." (PMID 26634162, 2015). "UC1/p-UC1 and UC2/p-UC2 expressed only luminal markers (KRT7, GATA3), supporting their classification as luminal-type urothelial carcinomas, while UC3/p-UC3 expressed basal markers (KRT5, KRT6) and KRT7 but lacked GATA3 and keratinization markers, confirming its basaloid subtype." (PMID 41387887, 2025).
melanoma (34 papers, 2011 to 2025). A malignant, usually aggressive tumor composed of atypical, neoplastic melanocytes. "We found that kallikrein-related peptidase 7 (KLK7) and keratin 7 (KRT7) were the most related genes in melanoma and renal cancer separately." (PMID 34603393, 2021). "In HUVECs co-cultured with melanoma cells there was a marked decrease in expression levels of several endothelial markers (KRT7, KRT18, TJP2), as well as a severe decrease in FST expression, an EMT/EndMT antagonist." (PMID 25742314, 2015). "The tumor cells showed positive immunoreactivity for cytokeratin 7 (CK7) and galectin-3 in the immunohistochemical staining, while exhibiting negative immunoreactivity for CK20, thyroid transcription factor-1 (TTF-1) and human melanoma black-45." (PMID 24932230, 2014). "Cytokeratin 7 (CK7) expression was positive in the primary EMPD and negative for CK20, Human melanoma black-45 (HMB-45), and CK5/6 expression." (PMID 39045556, 2024). "Histological examination of the brain tumor showed neural differentiation markers (thyroid transcription factor 1 (TTF-1), cytokeratin 7 (CK7), AE1/AE3, and epidermal growth factor receptor (EGFR)) with negative melanoma markers." (PMID 39192931, 2024). "Desmin, β-catenin, cytokeratin 7 (CK7), cytokeratin 20 (CK20), smooth muscle actin (SMA), epithelial membrane antigen (EMA), S100 protein, melanoma antigen (melan A), and human melanoma black (HMB45) were all negative precluding other diagnosis." (PMID 38098096, 2023). "Immunohistochemically, tumor cells were positive for cytokeratin and vimentin, but negative for cytokeratin 7 (CK 7), thyroid transcription factor-1 (TTF-1), carbonic anhydrase-9 (CA-9), paired box gene 8 (PAX8), leukocyte common antigen (LCA), and human melanoma black 45 (HMB45)." (PMID 33950950, 2021).
ovarian tumor (29 papers, 2011 to 2025). "Western blot analysis of primary ovarian tumors revealed that miR-675 expression led to the upregulation of epithelial markers cytokeratin-7 and E-cadherin, while mesenchymal markers N-cadherin, Vimentin, and Snail2 were downregulated." (PMID 39744561, 2025). "In addition, we also performed immunostaining on primary ovary tumor sections using survivin, vimentin, and cytokeratin-7." (PMID 30241553, 2018). "Of note, the aberrant expression of α- and β-tubulin, keratin 7, and other cytoskeleton regulators has been reported in drug-resistant ovarian tumors, indicating that dysregulation of the cytoskeleton may also contribute to multi-drug resistance." (PMID 21390237, 2011). "Mucinous ovarian tumors of non-teratomatous origin typically exhibit an immunophenotype akin to that of the upper gastrointestinal tract, characterized by the expression of Cytokeratin 7 (CK7)-positive and Cytokeratin 20 (CK20)-positive or -negative." (PMID 39040449, 2024). "Immunohistochemically, the ovarian tumor was negative for cytokeratin 7 (CK7), and positive for CK20 and caudal‐related homeobox 2 (CDX2)." (PMID 35251649, 2022). "Cytokeratin 7 and 20 (CK7 and CK20) are the most commonly determined antigens in ovarian tumors." (PMID 28730323, 2017).
oncocytoma (28 papers, 2009 to 2026). "Oncocytomas typically display overall scarce staining for cytokeratin 7 (CK7), apart from small clusters of cells or individual CK7+ cells." (PMID 35269747, 2022). "The immunoreactivity of chRCC to cytokeratin 7 was higher than that of oncocytomas and normal kidney." (PMID 20462447, 2010). "In contrast to oncocytoma, which typically shows a very small percentage of cells positive for keratin 7 in a scattered distribution, LOT is diffusely positive for this marker, a feature that would have likely led to consideration as eosinophilic chromophobe RCC by some in the past." (PMID 39287823, 2024). "Oncocytomas generally show very minimal staining for cytokeratin 7 (CK7), typically limited to scattered individual cells or small clusters of cells, whereas a classic example of chromophobe renal cell carcinoma (with pale-staining cytoplasm) is diffusely positive in a membranous distribution." (PMID 29090117, 2017). "Despite the shared molecular pathogenesis with LOT, keratin 7 shows only rare positivity in EVT, more like an oncocytoma pattern." (PMID 39287823, 2024). "Rare oncocytic renal tumors resemble oncocytoma, yet show diffuse keratin 7 (KRT7) staining and negative KIT staining, which would be unexpected for renal oncocytoma (RO)." (PMID 39980061, 2025). "Most of the pathologists noted that minimal staining for keratin 7 in a few scattered cells is expected in an oncocytoma, whereas a complete absent staining pattern was unusual (Question #13)." (PMID 39287823, 2024). "Chromophobe RCCs exhibit diffuse positivity for cytokeratin 7 (CK7), whereas oncocytomas are negative or present focal positivity for CK7." (PMID 37556095, 2023).
metastatic carcinoma (26 papers, 2008 to 2026). A carcinoma which has spread from the original site of growth to another anatomic site. "We report a rare case of metastatic carcinoma originating from a cecal adenocarcinoma with an unusual cytokeratin 7/cytokeratin 20 immunophenotype." (PMID 26810414, 2016). "The potential of KRT7 expression in distinguishing between primary cancer and metastatic carcinoma." (PMID 38260844, 2023). "Results revealed a higher Mesenchymal markers in primary cancer cells (e.g., NCAM1, LAMB1, SERPINE1, TCF4, VIM, ZEB1, and ZEB2) and a higher Epithelial markers in metastatic cancer cells (e.g., CDH1, CLDN4, ELF3, EPCAM, KRT18, KRT7, and KRT8)." (PMID 37202394, 2023).
metastatic tumors (26 papers, 2010 to 2026). "Patients with higher expression of KRT7 or MUC1 had a significantly poorer overall survival compared to those whose metastatic tumors exhibited lower expression levels of these genes." (PMID 38260844, 2023). "The cytokeratin 7/20 profile of a particular tumor has proved to be a useful aid in differential diagnosis of carcinomas, since primary and metastatic tumors tend to retain the cytokeratin profiles of the epithelium from which they arise." (PMID 22268990, 2012). "Surgical pathology results showed immunohistochemical staining positive for p40 and cytokeratin 7 (CK7) and morphologic features consistent with dermal primary with squamous differentiation strongly suggestive of metastatic disease." (PMID 38962613, 2024). "Immunohistochemistry demonstrated that these tumor cells were positive for both cytokeratin 7 (CK7) and thyroid transcription factor-1 (TTF-1) and were negative for both CK20 and thyroglobulin, which concords with metastatic disease from lung origin." (PMID 26410084, 2015). "A recent study showed that the CK7 (KRT7), CK20 (KRT20), and SATB2 immunohistochemical markers could assist in differentiating primary MCs from metastatic tumors." (PMID 36818673, 2022).
colonic adenocarcinoma (23 papers, 2002 to 2025). "These tumors showed atypical immunohistochemistry as a colonic adenocarcinoma: positive for cytokeratin 7, negative for cytokeratin 20, and negative for β-catenin nuclear accumulation." (PMID 26649222, 2015).
gastric adenocarcinoma (21 papers, 2008 to 2026). "In immunohistochemical studies the tumor cells showed a strong expression of cytokeratin 7 and focal expression of cytokeratin 20 consistent with the diagnosis of gastric adenocarcinoma." (PMID 18279511, 2008). "Immunohistochemical analysis showed that these cells expressed cytokeratin 7 but not cytokeratin 20, CD117, CD34, chromogranin A, and synaptophysin, confirming the diagnosis of exophytic gastric adenocarcinoma with peritoneal dissemination." (PMID 42017098, 2026).
prostate carcinoma (20 papers, 2009 to 2025). A carcinoma that arises from epithelial cells of the prostate gland. "Prostate carcinomas are considered KRT7-negative tumors and we confirmed that KRT7 expression was lost in tumoral cells and only sporadically found in advanced tumors." (PMID 35406395, 2022). "This study establishes keratin-7 expression in localized prostate cancer specimens as a promising biomarker of disease progression." (PMID 35406395, 2022). "In this study, the Cytokeratin 7 positivity was seen in 88.9% of bladder cancer versus 27.8% of prostate cancer samples." (PMID 33391378, 2021). "Most of the historical studies do not report any immunoreactivity of KRT7 in prostatic carcinomas, but some authors describe an “aberrant” KRT7 staining on rare individual cells within otherwise nonreactive tumor areas." (PMID 35406395, 2022). "In tumoral cores composed of luminal cells, no KRT7 expression was found, similarly to the description by some authors of prostate carcinoma as usually KRT7-negative." (PMID 35406395, 2022). "They concluded that even if prostate carcinomas were considered normally negative for KRT7, some tumors may exhibit KRT7 reactivity, ranging from a few scattered positive cells via positive tumor areas to homogeneously positive tumors." (PMID 35406395, 2022).